TRIB1 (tribbles pseudokinase 1)
Diseases named in the same sentence as TRIB1 in open-access papers (continued):
Sharing a sentence is not in itself a finding about the gene and the disease.
eczema (3 papers, 2021 to 2023). "In addition, a recent blockbuster study on eczema identified TRIB1/LINC00861 as one of the crucial variants, and this change is closely related to immune cell function." (PMID 37673886, 2023). "TRIB1 has also been found to be overexpressed in patients with HIV, and TRIB1 SNPs has been identified to be associated with inflammatory bowel disease (IBD) and eczema." (PMID 35205759, 2022).
Hypertension (3 papers, 2017 to 2024). The presence of chronic increased pressure in the systemic arterial system. "Rs2954029 (TRIB1) is associated with sleep regulation and increased expression during sleep deprivation, which in turn is closely correlated with stress whereas rs12190287 (TCF21) is a possible susceptibility locus for hypertension." (PMID 28426714, 2017).
hypertriglyceridemia (3 papers, 2015 to 2025). A laboratory test result indicating elevated triglyceride concentration in the blood. "M2 macrophages also contribute to the control of lipolysis and deficiency in tribbles pseudokinase 1 (Trib1), a protein that is essential for M2 macrophage differentiation, is associated with increased lipolysis and hypertriglyceridaemia in mice on a high‐fat diet." (PMID 41292129, 2025).
liver disease (3 papers, 2019 to 2025). "In consideration of the higher mortality rate of NAFLD-related CHD than the single liver disease, it is meaningful to investigate the effect of TRIB1 rs17321515 gene polymorphism on the risk of CHD in general population and NAFLD patients, and the effect on the serum lipids levels." (PMID 31470861, 2019). "We replicated previous GWAS results, reporting a significant association of TSLP and RORA gene variants with asthma and GCKR, PNPLA3, TRIB1 and TM6SF2 gene variants with the risk of developing liver diseases, notably NAFLD/NASH." (PMID 30978214, 2019).
liver fibrosis (3 papers, 2022 to 2025). "For instance, liver fibrosis is alleviated and neutrophil numbers are increased in the liver of Tribbles pseudokinase 1- (Trib1-) deficient mice treated with CCl4." (PMID 36299447, 2022). "Meanwhile, ECM1, TRIB1, and CYP2C19 were downregulated, implicating impaired liver fibrosis regulation, carcinogen metabolism, and potential disruption of key signaling pathways." (PMID 41216224, 2025).
lung carcinoma (3 papers, 2017 to 2023). "Interestingly, our data also indicated that the higher expression of TRIB1 was correlated with bad treatment response and poor overall survival than lower expression of TRIB1 group in lung cancer." (PMID 28406482, 2017). "Additionally, cBioPortal database analysis further revealed that frequency of the TRIB1 gene amplification in lung cancer specimens was 6 to 7%, suggesting a prooncogenic role of TRIB1 in NSCLC." (PMID 28406482, 2017). "Furthermore, cBioPortal database analysis also showed that amplification of TRIB1 was marginally related to a bad disease free survival of lung cancer patients (P=0.059)." (PMID 28406482, 2017).
ovarian carcinoma (3 papers, 2011 to 2015). A malignant neoplasm originating from the surface ovarian epithelium. "Trib1 is involved in the etiology of AML as well as ovarian cancer." (PMID 21811619, 2011). "In ovarian cancer, a few of the interesting interacting genes include MYC, a well-known oncogene and TRIB1, a novel regulator of the MAP kinase pathway recently linked to leukemogenesis." (PMID 23822816, 2013).
autoimmune disease (2 papers, 2011 to 2021). A disorder resulting from loss of function or tissue destruction of an organ or multiple organs, arising from humoral or cellular immune responses of the individual to their own tissue constituents. "TRIB1 is also involved in a series of non-neoplastic diseases, including metabolic disorders, cardiovascular diseases, and autoimmune diseases." (PMID 34539875, 2021). "Trib1 is a member of a recently identified protein family called tribbles, that function as dynamic interactors of MAPK proteins, regulating numerous signaling pathways that play a role in embryonic development and the development of human diseases, such as cancer and autoimmune disease." (PMID 21966443, 2011).
breast tumor (2 papers, 2022 to 2024). "Studies have shown that both overexpression and knockdown of TRIB1 in myeloid cells promote the growth of breast tumors in mice; myeloid TRIB1 is a negative regulator of the antitumor cytokine IL-15." (PMID 39376611, 2024). "Both overexpression and knockout of myeloid Trib1 promote mouse breast tumor growth, albeit through different molecular mechanisms." (PMID 35664073, 2022).
Disorder of lipid metabolism (2 papers, 2021 to 2026). "All lipid metabolism disorders caused by TRIB1 observed in these studies are discussed from the perspective of immune inflammation, and the relationship between TRIB1 and fat development remains to be explored." (PMID 34539875, 2021).
inflammatory bowel disease (2 papers, 2022 to 2024). A spectrum of small and large bowel inflammatory diseases of unknown etiology. "Knockout of mir-98-5p alleviates inflammatory bowel disease symptoms by increasing the expression of Trib1 and changing the polarization of macrophages to M2 phenotype." (PMID 39620221, 2024). "It was also reported that miR-98-5p could repress Trib1 expression while this miRNA has been shown to be increased in a mouse model of inflammatory bowel disease (IBD)." (PMID 35205759, 2022).
lupus (2 papers, 2018 to 2024). "Of note, TRIB1 is shown to negatively regulate B cells in systemic lupus erythematosus via its interaction with CD72, an effector of autoimmunity." (PMID 38791967, 2024). "In conclusion, we described a new role of Trib1 as a negative regulator of B cells.Despite the polygenic nature of lupus disease in humans, one feature of B cells fromquiescent SLE patients, i.e., Trib1 overexpression, in mice, is sufficient on its own tohave an immunosuppressive effect on B cells." (PMID 29599769, 2018). "Trib1-ROSA Mb1Cre mice were analyzed to evaluate the development of lupus symptoms.They do not develop any proteinuria, even at old age (18 months) (data notshown)." (PMID 29599769, 2018).
prostate tumor (2 papers, 2017 to 2018). "The increase in prostate tumor growth observed was reversed in a TRIB1 knockdown model." (PMID 30337939, 2018).
acute coronary syndrome (1 paper, 2025). Signs and symptoms related to acute ischemia of the myocardium secondary to coronary artery disease. "Focusing on the TRIB1 rs2954029 A/T SNP, having two copies of the T allele was linked to acute coronary syndrome (ACS) and, surprisingly, to higher levels of HDL-C." (PMID 40563858, 2025). "The aim of this work was to explore whether single nucleotide polymorphisms (SNPs) in the TRSP1 (rs231150 and rs2737229) and TRIB1 (rs2980880 and rs2954029) genes are involved in acute coronary syndrome (ACS) and plasma lipid levels." (PMID 40563858, 2025).
acute liver failure (1 paper, 2023). Rapid deterioration of liver function causing encephalopathy and coagulopathy. "Finally, correlation between Trib1 expression, Nrf2 nuclear localization, and cell proliferation was identified in liver specimens taken from patients with acute liver failure." (PMID 37355685, 2023). "In the second model in which C57/B6 mice were injected with a single dose of acetaminophen (APAP) to induce acute liver failure, similar observations were made that Trib1 expression was down-regulated at 1d and 2d in the liver after APAP injection, which mirrored PCNA/cyclin D1/CDK4 up-regulation." (PMID 37355685, 2023).
Autoimmunity (1 paper, 2018). The occurrence of an immune reaction against the organism's own cells or tissues. "Wenotably described for the first time in B cells the interaction between Trib1 and COP1,and with CD72, a negative regulator of B cells whose deficiency in mice leads to thedevelopment of autoimmunity." (PMID 29599769, 2018). "Interestingly, we find an interactionbetween Trib1 and CD72, a negative regulator of B cells whose deficiency in miceleads to the development of autoimmunity." (PMID 29599769, 2018). "As the role of Trib1 in B cells and in autoimmunity has never been described, wedecided to investigate in detail the possible role of TRIB1 overexpression in B cellfunction and in the promotion of SLE." (PMID 29599769, 2018).
diabetic nephropathy (1 paper, 2022). "As an example, the use of berberine has recently been shown to enhance Trib1 expression and reduce diabetic nephropathy in a mouse model." (PMID 35205759, 2022).
end-stage renal disease (1 paper, 2014). "Furthermore, TRIB1 expression was correlated to non-diabetic end-stage renal disease." (PMID 25540021, 2014).
gastric cancer (1 paper, 2023). A primary or metastatic malignant neoplasm involving the stomach. "Specifically focusing on gastric cancer cases (STAD) within the TCGA, we found a very low frequency of TRIBs genetic and genomic alterations (TRIB1: 9.4%, TRIB2: 2.1%, and TRIB3: 2.1%)." (PMID 38254916, 2023).
gastritis (1 paper, 2023). Inflammation of the stomach. "In this study, we screened 11 important lncRNAs (AFAP1-AS1, MIR155HG, LINC00472, and FAM201A) and mRNAs (CASP10, SLC26A2, TRIB1, BMP2K, SCAMP1, TNKS1BP1, and MBOAT2) according to the gene expression profiles of gastric epithelial tissues in different stages of Hp infection-induced gastritis." (PMID 37249580, 2023).
Glucose intolerance (1 paper, 2015). Glucose intolerance (GI) can be defined as dysglycemia that comprises both prediabetes and diabetes. "In one example, mice lacking Tribbles homolog 1 (Trib1, which encodes an adaptor protein involved in proteasome-mediated protein degradation) in hematopoietic cells develop glucose intolerance and insulin resistance on a high-fat diet." (PMID 26308623, 2015).
malignant glioma (1 paper, 2023). A grade III or grade IV glioma arising from the central nervous system. "Finally, TRIB1 overexpression increased tumor growth in an orthotopic xenograft mouse model of GBM suggesting that TRIB1 plays oncogenic role(s) in malignant gliomas." (PMID 37528172, 2023). "Taken together, these correlative studies suggest that TRIB1 may serve as a potential prognostic marker for malignant gliomas." (PMID 37528172, 2023).
myeloid neoplasm (1 paper, 2021). Proliferation of myeloid cells originating from a primitive stem cell. "While the importance of TRIB1 in myeloid neoplasms is well established, the function of TRIB1 in solid tumours is less well understood." (PMID 34205360, 2021). "Beyond myeloid neoplasms, TRIB1 plays diverse roles in signalling pathways with well-established roles in tumour progression." (PMID 34205360, 2021).
nasopharyngeal carcinoma (1 paper, 2024). A carcinoma arising from the nasopharyngeal epithelium. "Another example is a JUN-mediated seRNA, associated with metastasis (seRNA-NPCM), which forms an R-loop to simultaneously regulate distal target (NDRG1) and neighbouring (TRIB1) genes to promote the metastasis of nasopharyngeal carcinoma (NPC)." (PMID 38542080, 2024).
pancreatic cancers (1 paper, 2022). "Furthermore, scatter plot analyses showed significant positive correlations of SET/CIP2A expression with the expression levels of the IEGs (TRIB1, SPRY4, CTGF) and with those of growth-promoting genes (cyclin D1, E2, and PCNA) in KRAS-mutated pancreatic cancers." (PMID 36463234, 2022).
promyelocytic leukemia (1 paper, 2024). "TRIB1 overexpression causes resistance to ATRA (all-trans retinoic acid) treatment during acute promyelocytic leukemia in exclusively sensitive myeloid cells expressing the PML/RARA fusion protein by preventing their differentiation through the downregulation of C/EBPα." (PMID 38791967, 2024).
renal fibrosis (1 paper, 2020). A final common manifestation of a wide variety of chronic kidney diseases characterized by glomerulosclerosis and tubulointerstitial fibrosis. "The expression of the mouse renal fibrosis marker collagen I/III was obviously upregulated in the first 3 days and recovered to normal levels on day 28 in the model and Trib1-depletion groups." (PMID 32265926, 2020).
squamous cell carcinoma (1 paper, 2024). A carcinoma arising from squamous epithelial cells. "In this work, our screening uncovered previously unidentified prognostic gene expression indicators, namely, MYO1E, FAM83 homologs, and DKK1 for adenocarcinoma, and FGA and TRIB1 for squamous cell carcinoma." (PMID 39513892, 2024).
triple-negative breast carcinoma (1 paper, 2021). An invasive breast carcinoma which is negative for expression of estrogen receptor (ER), progesterone receptor (PR), and human epidermal growth factor receptor 2 (HER2). "TRIB1 knockdown in triple-negative breast cancer cells results in inhibited AKT1 phosphorylation and activity." (PMID 34205360, 2021). "In triple-negative breast cancer cells, TRIB1 was one of only six genes upregulated in both MDA-MB-231 and HS578T paclitaxel-resistant cells, indicating it is likely essential in the development of paclitaxel resistance." (PMID 34205360, 2021). "Regulation of NF-κB, via AKT1 inhibition, is purported to be critical in TRIB1 regulation of the cell cycle and TRAIL drug response in triple-negative breast cancer cells." (PMID 34205360, 2021).
tuberculosis (1 paper, 2024). A chronic, recurrent infection caused by the bacterium Mycobacterium tuberculosis. "TRIB1 is a predicted target of microRNA–gene interactions that differentiate active and latent TB patients and is an overabundant transcript in highly proinflammatory tuberculosis-immune reconstitution inflammatory syndrome patients." (PMID 38896446, 2024).
cancer (35 papers, 2011 to 2025). A tumor composed of atypical neoplastic, often pleomorphic cells that invade other tissues. "Here we describe our current knowledge of how TRIB1 structure and function are linked in the context of cancer." (PMID 34205360, 2021). "Genomic (amplification and microsatellite repeats) and epigenetic (microRNA-based regulation) alterations in the TRIB1 gene are linked to cancer." (PMID 32932846, 2020). "An increasing body of evidence suggests that TRIB1 controls cellular functions associated to cancer aggressiveness." (PMID 32932846, 2020). "In addition to cancer, TRIB1 has been implicated in metabolic and lipid disorders, according to several GWAS." (PMID 38791967, 2024). "TRIB1 has also been reviewed to be associated with drugresistance in various cancers." (PMID 39513892, 2024). "However, as the focus of this review is TRIB1 in cancer, the discussion of interaction partners is centred on purported TRIB1 interaction in cancer-associated signalling pathways." (PMID 34205360, 2021). "In addition to its contribution to cancers, genome-wide-association studies (GWAS) have uncovered a functional association of the TRIB1 locus with lipid traits, cardiovascular disease (CAD) as well hepatic steatosis, the accumulation of fat in the liver." (PMID 27019349, 2016). "Previous studies showed that Trib1 was associated with the pathogenesis of cancer." (PMID 26521947, 2015). "One such pseudokinase is mammalian tribbles homolog 1 (TRIB1), a member of the Tribbles family of pseudokinases, which has emerged to play a role in several diseases, including cancer, and is the focus of this review." (PMID 38791967, 2024). "In conclusion, targeting TRIB1 presents an opportunity for cancer treatment as well as other metabolic disorders in which TRIB1 has been shown to play a role." (PMID 38791967, 2024). "TRIB1 and pseudokinases in general have only recently gained limelight in the cancer field for providing a new insight into tumorigenic processes." (PMID 38791967, 2024). "In this review, we describe its role in immune cells and highlight TRIB1 interacting partners which suggests cell-specific functions and that TRIB1 is involved in cellular homeostasis and also in different cancers and immune-related disorders." (PMID 35205759, 2022). "Instead, in vitro TRIB1 knockdown in a model of human TAMs revealed that inhibition of TRIB1 enhances expression of oncogenic cytokines in TAMs, which are involved both in cancer cell survival and immune suppression." (PMID 35664073, 2022). "In this review, we describe its roles in immune cells and highlight the interacting partners explaining these functions which suggests TRIB1 as a precise mediator of cellular homeostasis as well as in different cancers and immune-related disorders." (PMID 35205759, 2022). "Regarding cancer, as the human TRIB1 gene is located at a chromosomal locus (8q24.13) near the MYC oncogene, it has been associated with multiple cancer types." (PMID 35205759, 2022).